RGS16 (regulator of G protein signaling 16)
Description:
Regulates G protein-coupled receptor signaling cascades. Inhibits signal transduction by increasing the GTPase activity of G protein alpha subunits, thereby driving them into their inactive GDP-bound form. Plays an important role in the phototransduction cascade by regulating the lifetime and effective concentration of activated transducin alpha. May regulate extra and intracellular mitogenic signals (By similarity).
Synonyms: RGS-r; A28-RGS14; A28-RGS14P
Tractability: Small molecule: a structure with a bound ligand is known. Antibody: its Gene Ontology location is reachable by antibodies, with high confidence. PROTAC: ubiquitination databases record sites on it; a small molecule that binds it is known.
Target class: Enzyme
Gene: Protein-coding gene on chromosome 1 (182,598,623 to 182,604,394, reverse strand). Ensembl gene ENSG00000143333.
Subcellular location: Membrane
Subcellular location (Human Protein Atlas): Cytosol
Pathways (Reactome):
Signal Transduction: G alpha (i) signalling events; G alpha (q) signalling events; G alpha (z) signalling events
Gene Ontology:
Molecular function: GTPase activator activity; protein binding; calmodulin binding; GTPase activity
Biological process: positive regulation of GTPase activity; G protein-coupled receptor signaling pathway; negative regulation of G protein-coupled receptor signaling pathway; regulation of G protein-coupled receptor signaling pathway; visual perception
Cellular component: cytoplasm; cytoplasmic side of plasma membrane; membrane; plasma membrane
Genetic constraint (gnomAD): Loss-of-function variants: 10 observed, 17.12 expected, observed/expected ratio (o/e) 0.58, 90% interval 0.36 to 0.99. The upper end of that interval is the gene's LOEUF score, 0.99, which puts it in group 4 of 6, group 1 being the genes least tolerant of losing a copy. Missense variants: 237 observed, 251.84 expected, observed/expected ratio (o/e) 0.94, 90% interval 0.85 to 1.05. Synonymous variants: 88 observed, 104.76 expected, observed/expected ratio (o/e) 0.84, 90% interval 0.71 to 1.
Homologues: Orthologues: chimpanzee RGS16 (99% identical), guinea pig RGS16 (89% identical), macaque RGS16 (89% identical), pig RGS16 (89% identical), dog RGS16 (88% identical), mouse Rgs16 (85% identical), rat Rgs16 (85% identical), zebrafish rgs8 (39% identical). Paralogues in human: RGS8 (50% identical), RGS3 (47% identical), RGS5 (46% identical), RGS4 (45% identical), RGS2 (42% identical), RGS18 (39% identical), RGS1 (37% identical), RGS12 (34% identical), RGS21 (33% identical), RGS20 (31% identical), RGS19 (31% identical), RGS13 (30% identical), and 11 more.
Diseases named in the same sentence as RGS16 in open-access papers:
RGS16 is named in the same sentence as 53 diseases in open-access papers, as found by Europe PMC text mining. Sharing a sentence is not in itself a finding about the gene and the disease. The quoted sentences say what the papers report.
breast carcinoma (10 papers, 2005 to 2025). "The implementation of tyrosine kinase inhibitors in therapy also causes decreased RGS16 expression in breast cancer cells." (PMID 35453754, 2022). "In parallel to the investigation of RGS16 in breast cancer, several relevant studies have also linked changes in RGS16 expression to poor prognosis of cancer." (PMID 36120550, 2022). "In light of the previous observations, reduced RGS16 expression is observed in the majority of breast cancers with mutations, which supports the existence of an association of phosphatidylinositol pathway activity regulation with RGS16 expression and breast cancer cell growth." (PMID 35453754, 2022). "In addition, RGS16 can inhibit the epidermal growth factor (EGF)-mediated proliferation of breast cancer cells; and it is also associated with lymph node metastasis of pancreatic cancer and may be a prognostic marker for pancreatic cancer." (PMID 29108247, 2017). "A previous research has confirmed that RGS16 curbs breast cancer cell growth by regulating the Phosphatidylinositol 3-Kinase (PIK3) signaling pathway." (PMID 40413527, 2025). "Conversely, high expression of RGS16 can inhibit breast cancer growth via the PI3K signaling pathway." (PMID 32319728, 2020). "In some patients with breast cancer, deletion of RGS16 promotes the activation of PI3K signaling pathway by growth factors and thus promotes tumor proliferation, HER2 activation, and resistance to chemotherapeutic drugs." (PMID 32319728, 2020). "The RGS16 promoter is located at a site that is vulnerable to allelic imbalances in a subset of breast cancers that can result in promoter methylation of RGS16 in 10% of these cancers." (PMID 25568667, 2014). "RGS16 locus is a site of genomic instability in (50% of 222) primary breast tumors and knockdown of RGS16 in breast cancer cell lines increases Epidermal Growth Factor (EGF) and Fetal Bovine Serum (FBS) initiated proliferation." (PMID 25568667, 2014). "Four of 12 target genes (RARβ2, CYP26A1, CRBP1, and RGS16) were upregulated by more than two-fold in both the RA-sensitive lung and breast cancer cells." (PMID 16012519, 2005). "An earlier publication on the relationship between RGS expression and RGS gene epigenetic modification indicated that the methylation status of RGS16 gene promoter was significantly increased in breast cancer cells, where the RGS16 protein expression was obviously reduced." (PMID 37118788, 2023). "It seems that RGS16 may play an important role in controlling breast cancer cell growth through its influence on the key pathway leading to cell death." (PMID 35453754, 2022). "Allelic imbalance mapping analysis verified that the 1q25.3 region where the RGS16 protein is located is highly unstable in breast tumors, and RGS16 expression was reduced in breast cancer samples due to allelic imbalance, intragenic chromosomal break points and methylation." (PMID 36120550, 2022). "RGS16 overexpression in breast cancer cells inhibits the cell prolife ration dependent on epidermal growth factor (EGF), and decreased RGS16 expression was associated with a reduction in the cell proliferation rate and an increased resistance to tyrosine kinase inhibitors." (PMID 35453754, 2022). "Functional and expression analysis of RGS16 has been performed in breast cancers." (PMID 25568667, 2014). "RGS4 functions in breast cancer cells through regulating its classical GAP activity, whereas RGS16 and RGS6 participate in the negative regulation of breast cancer cells in a GAP-independent manner." (PMID 37118788, 2023). "For example, some RGS proteins including RGS4, RGS16, RGS2, RGS6 and RGS17 negatively regulate the progression of breast cancer, whereas RGS20 protein exerts the positive effects on potentiating the carcinogenesis of breast cancer." (PMID 37118788, 2023).
breast carcinoma (continued). "The pattern of retinoid responsiveness for six of 13 target genes (RARβ2, CYP26A1, CRBP1, RGS16, DUSP6, EGR1) correlated with phenotypic retinoid sensitivity, across a panel of retinoid-sensitive or -resistant lung and breast cancer cell lines." (PMID 16012519, 2005). "Overall, these discoveries indicate that RGS16 has a critical effect in breast cancer progression through allelic analysis, δEF1 family protein inhibition and GPCR-independent pathways, demonstrating that RGS16 may be a novel therapeutic target in breast cancer." (PMID 36120550, 2022).
glioma (8 papers, 2020 to 2024). A benign or malignant brain and spinal cord tumor that arises from glial cells (astrocytes, oligodendrocytes, ependymal cells). "All these results revealed that RGS16 expression tightly associated with malignant progression of gliomas, which has been reported in other solid cancers." (PMID 32319728, 2020). "To evaluated the association between RGS16 mRNA expression and glioma patients’ clinical outcomes, we performed Kaplan‐Meier (K‐M) survival curve analysis with the data of 299 and 631 patients from the CGGA microarray database and TCGA RNA sequencing database, respectively." (PMID 32319728, 2020). "Higher expression of RGS16 is significantly correlated with poor prognosis of patients with gliomas." (PMID 37955724, 2023). "All these results indicated that RGS16 was a novel independent prognostic factor and played a crucial role in the malignant progress of glioma." (PMID 32319728, 2020). "Knockdown of RGS16 in glioma cell lines also showed that RGS16 promoted the malignant progress of glioma cell lines." (PMID 32319728, 2020). "Experiments in vitro suggested that RGS16 was overexpressed in glioma cell lines and promoted cell proliferation and migration via EMT process." (PMID 32319728, 2020). "In this study, we detected the molecular and clinical characterization of RGS16 through more than 1000 glioma samples from TCGA and CGGA databases." (PMID 32319728, 2020). "K‐M survival curve analysis and ROC curve analysis indicated that RGS16 was a novel prognostic factor in glioma patients." (PMID 32319728, 2020). "To explore the role of RGS16 in inflammatory activation in gliomas, we chose seven inflammatory metagenes described in previous studies to represent different inflammation response." (PMID 32319728, 2020). "Here, we performed comprehensive analysis for the expression characteristic of RGS16 in Chinese Glioma Genome Atlas (CGGA) microarray database with 301 patients and validated in The Cancer Genome Atlas (TCGA) microarray and RNA sequencing database." (PMID 32319728, 2020). "In this study, we believe that RGS16 played an important role in malignant progress of glioma and had potential to become a novel immune‐related biomarker." (PMID 32319728, 2020). "RGS16 plays an important role in glioma progression and serves as an independent prognostic factor, especially in GBM patients." (PMID 32319728, 2020). "The univariate and multivariate Cox regression analysis and ROC curve showed that RGS16 was an independent prognostic factor for glioma patients." (PMID 32319728, 2020). "Interestingly, FABP3 and RGS16 have been proposed as markers of invasive glioma, and EBF2 positively regulates neuronal migration." (PMID 35563134, 2022). "Other recent in vitro experiments have revealed that RGS16 is oversaturated in glioma cell lines and facilitates tumor cell proliferation and migration through the EMT process, suggesting the potential of RGS16 as a novel prognostic biomarker and therapeutic target." (PMID 36120550, 2022). "In conclusion, we found that RGS16 plays an important role in the malignant progression of glioma." (PMID 32319728, 2020). "However, only a few studies have reported that RGS16 was dysregulated in glioma tissues or cell lines." (PMID 32319728, 2020). "In this study, we identified RGS16 as a novel prognostic factor in glioma." (PMID 32319728, 2020). "To further confirm these functional roles of RGS16 in glioma, we performed experiments in vitro." (PMID 32319728, 2020). "Interestingly, we found that RGS16 not only played an important role in malignant progression of glioma, but was also tightly related to the immune and inflammatory response in glioma." (PMID 32319728, 2020). "Furthermore, to evaluate the function of RGS16 in glioma cell lines, transwell and cell scratch were performed." (PMID 32319728, 2020).
glioma (continued). "The results indicated that the silence of RGS16 expression suppressed the migration ability of glioma cell lines, Besides, the clonogenic assay showed that the proliferative capacity and clonogenicity of glioma cell lines were inhibited after transfection with RGS16 siRNA." (PMID 32319728, 2020). "Further understanding of the function role and expression pattern of RGS16 in gliomas may provide more accurate diagnosis and prognosis predictions of patients, as well as the improvement of personalized therapeutics of glioma." (PMID 32319728, 2020). "Although, in this study, the functions of RGS16 in gliomas were deeply analyzed and discussed, the relationship between RGS16 expression and the biological characteristics of glioma remains unclear." (PMID 32319728, 2020). "Biological implication of abnormal expression of RGS16 in glioma was also explored." (PMID 32319728, 2020). "High level of RGS16 commonly gathered in glioma of mesenchymal subtype and wild‐type IDH1." (PMID 32319728, 2020). "We found that the expression of RGS16 was positively related to the grade of glioma." (PMID 32319728, 2020). "What's more, the expression pattern and prognostic value of RGS16 in glioma are still unclear." (PMID 32319728, 2020). "Besides, we further detected the roles of RGS16 in several glioma cell lines." (PMID 32319728, 2020). "These analyses indicated that RGS16 might play a key role in the malignant progression of glioma." (PMID 32319728, 2020). "However, as a key member of RGS family, RGS16 has seldom been studied in glioma." (PMID 32319728, 2020). "Among them, RGS16, CLEC5A and TAGLN2 are key regulatory factors that promote glioma progression by activating the PI3K‐AKT pathway in gliomas." (PMID 38809929, 2024). "Bioinformatics analyses showed that RGS16 was involved in cell proliferation, migration, EMT, and immune and inflammatory response of glioma." (PMID 32319728, 2020). "Due to the significant biological heterogeneous between GBM and lower grade glioma (LGG), we further investigated the prognostic value of RGS16 in GBM patients in two databases." (PMID 32319728, 2020). "In consideration of heterogeneity across different grades of glioma, we compared expression levels of differentially expressed genes from the CGGA microarray dataset and found that RGS16 expression was positively correlated with tumor grade." (PMID 32319728, 2020). "Firstly, we detected RGS16 protein levels in H4, LN229, U87, U251, U118 glioma cell lines and human astrocytes (HA) cell line; the Western blot analysis indicated that LN229 had the highest expression level while HA had the lowest." (PMID 32319728, 2020). "Besides, RGS16 may also serve as a potential therapeutic target in glioma." (PMID 32319728, 2020). "The Chinese Glioma Genome Atlas (CGGA) microarray dataset was used to evaluate the expression preference, prognostic value, and biological functions of RGS16." (PMID 32319728, 2020). "Yet, three of them, FABP3, RGS16, and EBF2, are relevant for glioma biology." (PMID 35563134, 2022). "Gene ontology analysis, gene set enrichment analysis, and gene set variation analysis suggested that the overexpression of RGS16 tightly related to cell proliferation, migration, epithelial‐mesenchymal transition (EMT), immune and inflammatory response of glioma." (PMID 32319728, 2020). "To further investigate the biological functions of RGS16 in glioma progression, we performed Pearson correlation analysis to find out the genes that tightly correlated with RGS16 expression (Pearson |R| > 0.4) in CGGA and TCGA glioma samples." (PMID 32319728, 2020).
pancreatic cancer (7 papers, 2014 to 2023). "Analysis of pancreata harvested from postnatal day 29 (P29) mice demonstrated that Rgs16::GFP expression in pancreatic tumors is dependent on the (heterozygous) KrasG12D allele; KIC and KC mice had high Rgs16::GFP expression." (PMID 26438693, 2015). "Our study suggests that the loss of RGS16 promotes pancreatic cancer metastasis by removing the inhibitory function of RGS16 on cell migration and invasion." (PMID 25568667, 2014). "Furthermore, decreased expression of RGS16 was associated with poor pancreatic cancer patient survival indicating the potential of RGS16 as a pancreatic cancer prognostic marker." (PMID 25568667, 2014). "For example, in patients with pancreatic cancer with lymph node metastasis, the RGS16 and FosB expression is markedly reduced in pancreatic cancer andis closely associated with a decreased survival rate of patients." (PMID 36120550, 2022). "The combined approach of HTS and in vivo validation using our Rgs16::GFP reporter is a powerful innovation in pancreatic cancer research." (PMID 33244070, 2020). "Meanwhile, previous studies have found that the expression levels of RGS16 and FosB were significantly reduced in pancreatic cancer with lymph node metastasis." (PMID 32319728, 2020). "Orthotopic transplantation of Rgs16::GFP+ primary cells derived from PDA tumors at 6 weeks rapidly regenerated GFP-positive pancreatic cancer in duct-like structures in close proximity with vasculature in recipient NOD-SCID mice." (PMID 26438693, 2015). "In humans, Rgs16 expression was observed in ducts of pancreatic cancer patients prior to detectable metastasis." (PMID 26438693, 2015). "Expression of RGS16 mRNA was decreased in the pancreatic cancer cell lines tested compared to control." (PMID 25568667, 2014). "RGS16 inhibited EGF induced migration of BxPC-3 and AsPC-1 cells, we further investigated if RGS16 can inhibit EGF induced invasion of these pancreatic cancer cells using matrigel invasion chambers." (PMID 25568667, 2014). "We first investigated the relative expression of RGS16 mRNA in four pancreatic cancer cell lines (BxPC-3, MIA PaCa-2, PANC-1, and AsPC-1) in order to characterize the endogenous expression of RGS16." (PMID 25568667, 2014). "We chose to study the function of RGS16 in pancreatic cancer because only 5.7% (1 out of 17) of pancreatic tumors with lymph-node metastases had expression of RGS16 compared to 70.6% (12 out of 17) of pancreatic tumors with non-metastasized pancreatic cancer." (PMID 25568667, 2014). "To test the hypothesis that RGS16 inhibits pancreatic cancer cell migration, we exogenously expressed RGS16 in BxPC-3, PANC-1, and AsPC-1 cells with an adenoviral vector and used wound healing assays to measure cell migration." (PMID 25568667, 2014).